THUMPD1 (THUMP domain 1 NAT10 acetyltransferase adaptor )
Diseases named in the same sentence as THUMPD1 in open-access papers (continued):
Sharing a sentence is not in itself a finding about the gene and the disease.
cancer (continued). "In our study, the TMB and MSI were both positively correlated with THUMPD1 expression in COAD patients, which supports the proposal that THUMPD1 may be a potential indicator for drug responses in several cancer types like COAD." (PMID 34762107, 2021). "Although NAT10 and THUMPD1 work synergistically, their effects on prognosis of diverse cancer types are not totally the same." (PMID 34762107, 2021). "Thus, high THUMPD1 expression improved survival probability for KIRC patients, while it shortened the time of cancer progression for CESC and LICH patients." (PMID 34762107, 2021). "In addition, our analysis on TME demonstrated a close relationship between THUMPD1 expression and TMB, MSI and neoantigen in several cancer types, as well as the MMR and methyltransferase gene that showed a co-expression with THUMPD1." (PMID 34762107, 2021). "Most cancer tissues had higher THUMPD1 expression than corresponding normal tissues, such as adrenocortical carcinoma (ACC) and LIHC." (PMID 34762107, 2021). "Possibly, THUMPD1 activity may influence essential process of MMR and DNA methylation, which contribute to tumorigenesis and malignant progression in specific cancers." (PMID 34762107, 2021). "Finally, the correlation between THUMPD1 expression and PFI in 33 cancer types was analyzed." (PMID 34762107, 2021). "Thus, THUMPD1 may be not a universal biomarker for all the cancers, but a potential predictor for prognosis of some cancer types and a valuable target worth further exploration in the mechanism of tumorigenesis." (PMID 34762107, 2021).
neurological diseases (2 papers, 2021 to 2024). "Based on our results, one plausible explanation for the neurological disorder of patients with bi-allelic THUMPD1 mutations is that one or more tRNAs is destabilized due to the loss of ac4C, resulting in degradation of those tRNAs by the RTD pathway." (PMID 38295128, 2024).
THUMPD1 also shares sentences with these, for which no sentence is quoted: cognitive deficits (1 paper); colon adenocarcinoma (1); colon cancer (1); developmental delay (1); Fanconi anemia (1); gastric cancer (1); Hypertension (1); low grade glioma (1); lung adenocarcinoma (1); lymphoma (1); mesothelioma (1); metabolic disorders (1); ovarian serous cystadenocarcinoma (1); pheochromocytoma (1); sarcoma (1); speech delay (1); theileriasis (1); triple-negative breast carcinoma (1); uterine carcinosarcoma (1); uterine corpus endometrial carcinoma (1).